MIRLET7B (microRNA let-7b)
Synonyms: hsa-let-7b; LET7B; MIRNLET7B; let-7b
Gene: MicroRNA gene on chromosome 22 (46,113,686 to 46,113,768, forward strand). Ensembl gene ENSG00000284520.
Gene Ontology:
Biological process: miRNA-mediated post-transcriptional gene silencing
Cellular component: RISC complex
Diseases named in the same sentence as MIRLET7B in open-access papers:
MIRLET7B is named in the same sentence as 7 diseases in open-access papers, as found by Europe PMC text mining. Sharing a sentence is not in itself a finding about the gene and the disease. The quoted sentences say what the papers report.
emphysema (1 paper, 2024). "We demonstrate that loss of the Mirlet7b/Mirlet7c2 cluster in T cells predisposed mice to exaggerated CS- or nCB-elicited emphysema." (PMID 38722677, 2024). "In the present study, we established that the Mirlet7 family members encoded by the Mirlet7b/Mirlet7c2 and Mirlet7a1/Mirlet7f1/Mirlet7d clusters are downregulated in T cells from lungs of emphysema patients and emphysematous mice that were exposed to CS or nCB." (PMID 38722677, 2024). "Consistently, the analogous murine Mirlet7b/Mirlet7c2 and Mirlet7a1/Mirlet7f1/Mirlet7d clusters, respectively, were similarly downregulated in pre-clinical emphysema models." (PMID 38722677, 2024). "Nonetheless, unbiased omics-based methods will be needed to determine if other gene targets beyond RORγt synergistically potentiate the in vivo Tc17 response and emphysema phenotype in context of deletion of Mirlet7b/Mirlet7c2 cluster." (PMID 38722677, 2024). "Mechanistically, our studies suggests that Mirlet7b/Mirlet7c2 cluster prevents the emergence of CD8+ T cell differentiation into Tc17 cells during emphysema in part, by directly silencing of Rorc." (PMID 38722677, 2024). "Correspondingly, we demonstrated that in vivo genetic ablation of Mirlet7b/Mirlet7c2 further sensitized mice to lung tissue destruction and emphysema upon treatment with nCB or CS." (PMID 38722677, 2024). "Paralleling our observations in human COPD and emphysema, mice with CS- or nCB-induced emphysema exhibited reduced expression levels of pri-Mirlet7b/c2 and pri-Mirlet7a1/f1/d transcripts in the lung and from isolated lung CD4+ and CD8+ T cells." (PMID 38722677, 2024). "Next, we elucidated Mirlet7b/Mirlet7c2 and Mirlet7a1/Mirlet7f1/Mirlet7d cluster expression (herein referred to as Mirlet7bc2 and Mirlet7afd, respectively) in murine models of CS- or nCB-induced emphysema, respectively." (PMID 38722677, 2024). "In support of our original hypothesis, the CD4+ T cell expression of Mirlet7a, Mirlet7b, Mirlet7d, and Mirlet7f were all inversely correlated with more severe emphysema distribution in the lungs as determined by Computed Tomography (CT) scan." (PMID 38722677, 2024). "miRNA expression-based studies have shown frequent downregulation of members of the Mirlet7 family, including Mirlet7a, Mirlet7b, Mirlet7c, Mirlet7d, Mirlet7e, and Mirlet7f in human emphysematous lung tissue and in murine models of emphysema, but the mechanism(s) of action remain ill-defined." (PMID 38722677, 2024). "Here, we show that overall expression of the Mirlet7 clusters, Mirlet7b/Mirlet7c2 and Mirlet7a1/Mirlet7f1/Mirlet7d, are reduced in the lungs and T cells of smokers with emphysema as well as in mice with cigarette smoke (CS)- or nCB-elicited emphysema." (PMID 38722677, 2024). "Furthermore, ablation of the Mirlet7b/Mirlet7c2 cluster enhanced CD8+IL17a+ T cells (Tc17) formation in emphysema development in mice." (PMID 38722677, 2024).
cancer (2 papers, 2018 to 2019). A tumor composed of atypical neoplastic, often pleomorphic cells that invade other tissues. "Moreover, the target gene MIR29C could promote cancer cell proliferation and migration, suppressing apoptosis; the target gene MIRLET7B, which was affected by DNA methylation, could cause the proliferation and migration of PTC." (PMID 31126066, 2019). "Target gene MIRLET7B is modified by DNA methylation to induce its expression inactivation that could upregulate the expression of cancer gene and subsequently cause transforming growth factor TGFβ/smad protein and Wnt/β-catenin signaling pathway to promote cancer cell proliferation and migration." (PMID 31126066, 2019).
MIRLET7B also shares sentences with these, for which no sentence is quoted: breast carcinoma (3 papers); endometriosis (1); glioblastoma (1); liver cancer (1); tumour (1).